EZH2 (enhancer of zeste 2 polycomb repressive complex 2 subunit)
Diseases named in the same sentence as EZH2 in open-access papers (continued):
Sharing a sentence is not in itself a finding about the gene and the disease.
chordoma (14 papers, 2016 to 2024). Chordomas are rare malignant tumors arising from embryonic remnants of the notochord in axial skeleton. "We first analyzed the RNA sequencing data of skull base chordoma that our previous study reported, and found high EZH2 expression was associated with shorter progression-free survival (P = 0.016)." (PMID 38882008, 2024). "An increase in EZH2 expression correlates with tumor aggressiveness, and specifically, this mechanism has been associated with the progression of chordomas." (PMID 39199581, 2024). "We found copy number gain mediated high EZH2 expression is associated with tumor stemness, M2 macrophage infiltration, and adverse prognosis in chordoma." (PMID 38882008, 2024). "In our work, we first established and characterized the largest panel of chordoma xenografts to date and, secondly, demonstrated a dramatic in vivo effect of the EZH2-inhibitor tazemetostat in one mutated PBRM1 chordoma PDX model." (PMID 35326637, 2022). "The first demonstration of a high antitumor activity of tazemetostat in a PDX model harboring a PBRM1 variant supports further evaluation for EZH2-inhibitors in this subgroup of chordomas." (PMID 35326637, 2022). "Next, we focused on the association between EZH2 and tumor immune microenvironment in chordoma." (PMID 38882008, 2024). "In this study, RNA sequencing and whole genome sequencing data based on 48 skull base chordomas as well as immunohistochemistry of paraffin sections were analyzed to elucidate the role of EZH2 in skull base chordoma." (PMID 38882008, 2024). "Cell counting kit-8 assay revealed that the proliferation ability of chordoma cells significantly decreased after the knockdown of EZH2 using siRNA in chordoma cells." (PMID 38882008, 2024). "Building on this foundation, the study delves into the immunologic correlates of the abscopal effect in chordomas following EZH2 inhibition and RT." (PMID 38731241, 2024). "In one PBRM1-mutated model, we demonstrated a strong therapeutic efficacy of the EZH2-inhibitor tazemetostat, encouraging further research on EZH2-inhibitors in chordomas." (PMID 35326637, 2022). "LOC554202 was shown to modulate chordoma cell invasion and growth by recruiting EZH2 to epigenetically regulate miR-31 expression." (PMID 31534128, 2019). "A phase I trial on the EZH2 inhibitor tazemetostat, confirmed complete or partial responses were observed in two children with chordoma according to RECIST (NCT02601937)." (PMID 30775316, 2019). "Thus, clinical trials on inhibitors of the EZH2 enzyme are currently underway in tumors with complete loss of SMARCB1/INI1 expression, including poorly differentiated chordomas (ClinicalTrials.gov Identifiers: NCT02601950 and NCT05407441)." (PMID 39199581, 2024). "Lastly, we validated the function of EZH2 in two chordoma cell lines (UM-Chor1 and MUG-Chor1)." (PMID 38882008, 2024). "Moreover, the transwell assay demonstrated that the invasion and migration of chordoma cells in the EZH2 knockdown group were visibly reduced compared with the cells in the control group." (PMID 38882008, 2024). "To explore the mechanism of EZH2 in chordoma, we further analyzed the differentially expressed genes (P < 0.05, |log fold change (FC)| > 0.5) between the high and low EZH2 groups and found significant differences in the expression of histone coding genes between the two groups." (PMID 38882008, 2024). "Moreover, we demonstrated that EZH2 promotes the proliferation, migration, and invasion of chordoma cells in in vitro cell experiments." (PMID 38882008, 2024). "Moreover, as shown in other human cancer types, further study combining EZH2-inhibitors with other treatments, such as immunotherapy or targeted therapies in chordomas, should also be considered to improve the outcome of chordoma patients." (PMID 35326637, 2022). "Notably, SMARCB1 was shown to repress EZH2 and, accordingly, high levels of EZH2 have been reported in SMARCB1-deficient tumors, including ES, AT/RT, MRT and chordomas." (PMID 36078034, 2022).
chordoma (continued). "Supporting the future consideration of EZH2 inhibitors as immune-modulatory therapeutics is a published case study in which a metastatic chordoma patient was placed on a tazemetostat, an EZH2 inhibitor, regiment before receiving radiotherapy at the primary tumor site." (PMID 33117406, 2020). "Therefore, EZH2 inhibitors (Tazemetostat) may prove to be beneficial in treating conventional chordoma, as recently demonstrated in vitro and in vivo studies and in patient-derived xenograft model." (PMID 37456229, 2023). "Moreover, we established for the first time a strong antitumor effect of the EZH2-inhibitor tazemetostat in a PBRM1-mutated PDX, suggesting PBRM1 as a new potential theragnostic marker in chordoma and supporting further evaluation of EZH2-inhibitors in this subgroup of chordomas." (PMID 35326637, 2022). "Promising efficacy has been suggested with EZH2 inhibitors, especially in SMARCB1/INI1 tumors, including chordomas." (PMID 35326637, 2022). "Those mutations lead to an upregulation of the enhancer of zeste homolog 2 (EZH2) activity, a subunit of Polycomb repressive complex 2 (PRC2), known as a tumor driver and thus a potential therapeutic target in chordomas." (PMID 35326637, 2022). "Beyond ES, EZH2 inhibitors have also shown efficacy in other SMARCB1-defective diseases in children, such as chordoma or ATRT, with 50% and 19% response rates, respectively." (PMID 35327458, 2022). "Although an efficient antitumoral activity of the anti-EZH2 tazemetostat has already been reported in one SMARCB1/INI1 negative chordoma, there are no data concerning anti-EZH2 drugs on PBRM1-mutated chordoma, which is one of the most common genetic type." (PMID 35326637, 2022). "For example, MIR31HG could enhance proliferation, migration and invasion by up-regulating EZH2/miR-31 and then indirectly activating the oncogene RNF144B in chordoma." (PMID 32280307, 2020). "However, the prognostic value and the mechanism of EZH2 have not been investigated in chordoma." (PMID 38882008, 2024). "For controls, we used liposarcoma and chordoma cell lines, not known to have alterations in SWI/SNF members or EZH2." (PMID 27125524, 2016).
chronic myeloid leukemia (14 papers, 2014 to 2025). "EZH2 mutations have also been observed in chronic myeloid leukemia (CML)." (PMID 32650416, 2020). "Silencing of EZH2 was reported to decrease XIAP expression in chronic myeloid leukemia cells." (PMID 30854231, 2019). "We next explored the embedded “expression” and “regulation” tracks using UCSC genome browser to further explore if in fact histone modifications such as EZH2 mediated H3K27Me3 is observed on ID4 promoter in cells that lack ID4 expression such as chronic myelogenous leukemia cell line K562." (PMID 25115397, 2014). "In cases of chronic myeloid leukemia (CML), EZH2 is often characterized by its overexpression." (PMID 40700255, 2025).
clear cell renal cell carcinoma (14 papers, 2017 to 2023). "For example, the SF SF3B3 is upregulated and contributes to tumorigenesis by regulating EZH2 pre-mRNA splicing, representing a key prognostic factor and therapeutic target in clear cell renal cell carcinoma." (PMID 33842332, 2021). "In renal clear cell carcinoma, higher expression of EZH2 and EED was significantly correlated with poor prognosis, whereas high levels of SUZ12 were associated with longer survival." (PMID 34202528, 2021). "The interaction between LINC-PINT and EZH2 has been mentioned in clear cell renal cell carcinoma (ccRCC)." (PMID 34257531, 2021). "In clear cell renal cell carcinomas (ccRCCs), a high expression of EZH2 has been correlated with bad prognosis, metastasis, and high grade tumors." (PMID 34991274, 2018). "Binding targets of SUZ12 and EZH2 were consistently enriched across all five cancer types, while targets of REST and SMAD4 were enriched in all cancers except for clear cell renal cell carcinoma." (PMID 31523055, 2019). "High expression levels of EZH2 and VEGF correlate with TMN stage and distant metastasis in advanced clear renal cell carcinoma." (PMID 28410242, 2017).
gallbladder cancer (14 papers, 2018 to 2024). "For example, our previous study showed that lncRNA MALAT1 enhanced the proliferative capability of gallbladder cancer cells by epigenetically recruiting the enhancer of EZH2 to the ABI3BP promoter region." (PMID 37564197, 2023). "For example, MINCR upregulates the expression of EZH2 by sponging miR-26a, which further enhances the MYC/miRNA/EZH2 axis in gallbladder cancer." (PMID 37215074, 2023). "In this study, we revealed MEG3-mediated targeting of EZH2 to ubiquitination and degradation, which is consistent with a previous study in gallbladder cancer." (PMID 35256601, 2022). "LncRNA MEG3 suppresses the progression of gallbladder cancer by promoting the ubiquitination of EZH2 to regulate LATS239." (PMID 33568633, 2021). "Long noncoding RNA MEG3 regulates LATS2 by promoting the ubiquitination of EZH2 and inhibits proliferation and invasion in gallbladder cancer." (PMID 34789260, 2021). "It was reported that the miR-217 could regulate the EZH2 expression in gallbladder cancer, we sought to explore whether circTP63 expression could affect EZH2 expression." (PMID 34789260, 2021). "MEG3 and UCA1 could both target Enhancer of Zeste Homolog 2 (EZH2), despite their differential roles in gallbladder cancer." (PMID 31297033, 2019). "In Gallbladder cancer, lncRNA MEG3 performs functions by regulating the stability of EZH2 to regulate the downstream target gene LATS2 and thereby inhibits invasion and proliferation." (PMID 34131399, 2021). "MEG3 is a lncRNA closely related to EZH2, and MEG3 attenuates EZH2 by increasing its ubiquitination in gallbladder cancer." (PMID 33061817, 2020).
lung squamous cell carcinoma (14 papers, 2016 to 2025). "The EZH2 gene expression of lung squamous cell carcinoma was positively correlated with the gene expression of BRAF (r = 0.3662, p < 0.0001) and KRAS (r = 0.3567, p < 0.0001)." (PMID 37069494, 2023). "EZH2 and BMI1 are similarly involved in lung tumour development, with EZH2 found highly expressed in squamous lung cell carcinoma together with BMI1 and the cellular proliferation marker Ki67." (PMID 33804165, 2021). "In lung squamous cell carcinoma, EZH2 expression is positively correlated with EGFR expression, but the correlation is weak (r = 0.1122 and p < 0.001)." (PMID 33299862, 2020). "In lung squamous cell carcinoma, a positive yet weak correlation was observed between EZH2 expression and EGFR expression (r = 0.1122 and p < 0.001)." (PMID 33299862, 2020). "In 261 cases of lung squamous cell carcinoma, EZH2 mRNA had a high expression with a median survival time of 52.97 months, and in 263 cases, there was a low expression with a median survival time of 62.00 months (HR = 1.03 and 95% CI 0.81−1.3; p = 0.82)." (PMID 33299862, 2020). "In this study, we examine whether inhibition of the methyltransferase enhancer of zeste homolog 2 (EZH2) can increase ICI response in lung squamous cell carcinomas (LSCC)." (PMID 38265267, 2024). "EZH2 expression was positively correlated with BRAF expression (r = 0.2397 and p < 0.001), especially in lung squamous cell carcinoma (r = 0.3662 and p < 0.001)." (PMID 33299862, 2020).
acute kidney injury (13 papers, 2018 to 2026). Sudden and sustained deterioration of the kidney function characterized by decreased glomerular filtration rate, increased serum creatinine or oliguria. "This study identifies a molecular mechanism of the O-linked N-acetylglucosamine transferase (OGT)-mediated enhancer of zeste homolog 2 (EZH2)/krüppel-like factor 2 (KLF2)/chemokine (C-X-C motif) ligand 1 (CXCL1) axis underlying the hypercalcemia-induced nerve injury in renal failure." (PMID 34462420, 2021). "Furthermore, inhibition of the EZH2/p38 signalling pathway has been shown to decrease apoptosis and inflammation, and improve renal function in acute kidney injury induced by ischemia–reperfusion." (PMID 38580969, 2024). "Reportedly, Targeting EZH2 protects against acute kidney injury via Raf-1/ERK1/2 pathway." (PMID 39308866, 2024). "In this study, EZH2 existed in the renal failure-related candidate genes." (PMID 36050772, 2022). "EZH2 also contributes to the pathogenesis of acute kidney injury (AKI)." (PMID 31866860, 2019). "Despite the established oncogenic and profibrotic functions of enhancer of zeste homolog 2 (EZH2), a methyltransferase that induces histone H3 lysine 27 trimethylation (H3K27me3), its role in acute kidney injury (AKI) remains unclear." (PMID 30341286, 2018). "By repressing PTEN via this mark, EZH2 activates pro-fibrotic signaling that drives epithelial-mesenchymal transition and fibrosis during acute kidney injury (AKI)-to-CKD progression." (PMID 41607591, 2026). "ZLD1039, a selective inhibitor of EZH2, has demonstrated protective effects against cancer and acute kidney injury (AKI)." (PMID 40478495, 2025). "It has been reported that inhibition of EZH2 could relieve acute kidney injury." (PMID 36050772, 2022). "The overexpression of EZH2 has been demonstrated to be related to acute kidney injury (AKI)." (PMID 36077742, 2022). "Taken together, silencing OGT downregulates EZH2, which increases the expression of KLF2 and then decreases the expression of CXCL1, thus alleviating hypercalcemia-induced nerve injury in renal failure." (PMID 34462420, 2021). "In the current study, we explored the regulatory mechanism of OGT in hypercalcemia-induced nerve injury in renal failure and found that OGT promotes this injury by regulating the EZH2/KLF2/CXCL1 axis." (PMID 34462420, 2021).
cutaneous melanoma (13 papers, 2015 to 2024). A primary melanoma arising from atypical melanocytes in the skin. "EZH2 expression is associated with high proliferation rates and aggressive tumor subgroups of cutaneous melanoma." (PMID 34063443, 2021). "We expressed multiple EZH2 GOF mutations in the A375 metastatic skin melanoma cell line and observed both increased H3K27me3 and dramatic changes in 3D culture morphology." (PMID 25671303, 2015). "In line with this idea, previous clinical data have demonstrated an association between EZH2 levels and aggressive features of cutaneous melanoma." (PMID 25671303, 2015). "The frequency of gain-of-function in EZH2 demonstrated a higher percentage in ovarian serous cystadenocarcinoma patients (11.4%, 66 cases) than in skin cutaneous melanoma patients (5.7%, 21 cases)." (PMID 29459674, 2018). "In addition, hyperactive EZH2 mutations are reported to control cell growth and metastasis through silencing of distinct tumor suppressors, such as DCK, AMD1, and WDR19, in cutaneous melanoma." (PMID 32906688, 2020). "In The Cancer Genome Atlas (TCGA), we found a significant correlation (r = 0.5; p ≤ 0.0001) between EZH2 and PLK1 expression in the cutaneous melanoma cohort." (PMID 36768289, 2023).
diabetic nephropathy (13 papers, 2020 to 2026). "In summary, we show that AGEs induce epigenetic changes in proximal tubular cells by suppressing EZH2, thereby facilitating the transcription of genes involved in progression of diabetic nephropathy." (PMID 41227374, 2025). "On the other hand, the role of WT-1/EZH2/β-catenin was earlier confirmed with regard to podocyte integrity in a diabetic nephropathy model." (PMID 41282610, 2025). "In the current study, we confirmed diminished NO level in kidney tissues of rats with diabetic kidney disease with a concurrent increase in EZH2 and H3K27me3 level." (PMID 40289112, 2025). "MiR-29b-3p suppresses the progression Of diabetic nephropathy (DN) in mice by inhibiting the expression of Enhancer of Zeste Homolog 2 (EZH2)." (PMID 38204237, 2024). "Blocking EZH2 can attenuate podocyte injury in diabetic nephropathy via mediating β-catenin inactivation." (PMID 35559246, 2022). "Consistently, Wan’s research demonstrates that a decrease of EZH2 is beneficial for podocyte injury by antagonizing Wilm’s tumor 1 (WT1) in diabetic nephropathy." (PMID 32508971, 2020). "We recently reported that AGEs reduce EZH2 expression in podocytes, lowering the repressive mark H3K27me3 and inducing the expression of Snai1, p27Kip1, and Tgf-β, thereby promoting podocytes damage and diabetic nephropathy." (PMID 41227374, 2025). "Furthermore, these findings extend our prior observation in podocytes, demonstrating the AGE-induced suppression of EZH2 contributes to epigenetic reprogramming and gene expression changes relevant to diabetic kidney disease." (PMID 41227374, 2025). "Furthermore, we also assessed the level of EZH2 and its catalytic product in rat kidney tissues with established diabetic kidney disease." (PMID 40289112, 2025). "Additionally, previous studies show crosstalk between WT-1 and β-catenin as a protective element of podocyte against diabetic nephropathy via the repression of EZH2/β-catenin." (PMID 41282610, 2025). "The repressed EZH2 was unfolded to aid in alleviating podocyte injury in diabetic nephropathy." (PMID 34857740, 2021). "EZH2 antagonized by Wilm’s tumor 1 could impair renal function while increasing podocyte injury in diabetic rats and patients with diabetic nephropathy." (PMID 34462420, 2021). "Also, in a diabetic nephropathy model, TGFβ-induced pro-fibrotic genes such as connective tissue growth factor (Ctgf) and serpin family E member 1 (Serpine1) are increased when Ezh2 is depleted by siRNA in renal mesangial cells." (PMID 34070078, 2021). "However, the role of EZH2 in diabetic nephropathy is controversial." (PMID 35559246, 2022). "However, the role of EZH2 in diabetic nephropathy is still controversial." (PMID 35559246, 2022). "Notably, EZH2 was found to aid in the promotion of fibrosis of diabetic nephropathy." (PMID 34857740, 2021). "Targeting EZH2 and the H3K27me3 pathway may represent a therapeutic strategy to mitigate AGE-induced renal injury and progression of diabetic kidney disease." (PMID 41227374, 2025).
myeloid leukemia (13 papers, 2011 to 2025). A clonal proliferation of myeloid cells and their precursors in the bone marrow, peripheral blood, and spleen. "By examining publically available data in the UCSC genome browser database, Myc was observed to associate upstream of the EZH2 transcription start site in K562 human myelogenous leukaemia cells and GM12878 lymphoblastoid cells." (PMID 21941025, 2011). "Within the UKBB, a GWAS for ICD-10 code C92 Myeloid leukaemia showed the strongest association with pLoF variants in the genes TET2 (P = 1.53e−25, β = 0.176629), EZH2 (P = 1.53e−8, β = 0.430923), and CHEK2 (P = 5.78e−7, β = 0.092176)." (PMID 40335619, 2025). "It has been reported that EZH2 inactivation and oncogenic NRAS mutations together activate BCAT1, enhance BCAA metabolism and mTOR signaling, and promote the development of myeloid leukemia." (PMID 39324007, 2024). "In regards to the regulation of the posterior HOXA cluster by ASXL1, there is one proposed mechanism from a study in ASXL1-/- myeloid leukemia cells, which showed global depletion of H3K27me3 and EZH2 at the posterior HOXA cluster." (PMID 35361921, 2022). "It has also been shown that Ezh2 directly regulates Egr1 in hematopoiesis, and that deletion of Ezh2 and the reactivation of genes repressed by it, including Egr1, converted a high-grade myeloid leukemia to a less aggressive myeloid neoplasia (MPN)." (PMID 29050203, 2017). "Overall, EZH2 aberrations and PRC2 deregulation seem to be extremely prevalent in myeloid leukemia, hence, targeting EZH2 dysfunction directly or indirectly seems to be a promising approach for many patients." (PMID 36338673, 2022). "Overall, EZH2 aberrations and PRC2 dysregulation seem to be extremely prevalent in myeloid leukemia." (PMID 32650416, 2020). "For instance, targeting EZH2 could deplete HOXA9 and Meis1 levels in THP1 cells and disrupt the biological synergy between the two genes in inducing myeloid leukemia." (PMID 25944687, 2015).